IQCE (IQ motif containing E)
Description:
Component of the EvC complex that positively regulates ciliary Hedgehog (Hh) signaling (By similarity). Required for proper limb morphogenesis.
Synonyms: KIAA1023; 1700028P05Rik; PAPA7
Tractability: Antibody: UniProt places it where antibodies can reach, with medium confidence; its Gene Ontology location is reachable by antibodies, with medium confidence; the Human Protein Atlas places it where antibodies can reach. PROTAC: ubiquitination databases record sites on it.
Gene: Protein-coding gene on chromosome 7 (2,558,972 to 2,614,733, forward strand). Ensembl gene ENSG00000106012.
Subcellular location: Cell projection, cilium membrane
Subcellular location (Human Protein Atlas): Nucleoplasm; Plasma membrane; Nuclear membrane; Primary cilium
Pathways (Reactome):
Signal Transduction: Activation of SMO
Gene Ontology:
Molecular function: protein binding
Biological process: limb morphogenesis
Cellular component: cilium; ciliary membrane
Genetic constraint (gnomAD): Loss-of-function variants: 95 observed, 78.11 expected, observed/expected ratio (o/e) 1.22, 90% interval 1.03 to 1.44. The upper end of that interval is the gene's LOEUF score, 1.44, which puts it in group 5 of 6, group 1 being the genes least tolerant of losing a copy. Missense variants: 942 observed, 819.98 expected, observed/expected ratio (o/e) 1.15, 90% interval 1.09 to 1.21. Synonymous variants: 381 observed, 339.42 expected, observed/expected ratio (o/e) 1.12, 90% interval 1.03 to 1.22.
Homologues: Orthologues: chimpanzee IQCE (98% identical), macaque IQCE (90% identical), pig IQCE (68% identical), dog IQCE (64% identical). Paralogues in human: IQCN (18% identical).
Diseases named in the same sentence as IQCE in open-access papers:
IQCE is named in the same sentence as 12 diseases in open-access papers, as found by Europe PMC text mining. Sharing a sentence is not in itself a finding about the gene and the disease. The quoted sentences say what the papers report.
allergic rhinitis (1 paper, 2022). Inflammation of the nasal mucous membranes caused by an IgE-mediated response to external allergens. "ZNF804A, XKR6, and IQCE genes have also been linked to other diseases, such as bipolar disorder, schizophrenia, memory loss, longevity, blood metabolite levels, asthma, and allergic rhinitis." (PMID 36233348, 2022).
endometrial cancer (1 paper, 2024). Primary or metastatic malignant neoplasm involving the endometrium (mucous membrane that lines the endometrial cavity). "While the functions of FRMD3 and IQCE remain unclear, IQCE expression is associated with improved survival of diffuse-type gastric cancer and good prognosis of endometrial cancer." (PMID 38398114, 2024).
melanoma (1 paper, 2020). A malignant, usually aggressive tumor composed of atypical, neoplastic melanocytes. "We constructed a 6-gene signature (IQCE, RFX6, GPAA1, BAHCC1, CLEC2B, and AGAP2) as a novel prognostic marker for predicting the survival of melanoma patients." (PMID 32462000, 2020). "In addition, immunohistochemistry analysis demonstrated that IQCE, RFX6, GPAA1, BAHCC1, CLEC2B, and AGAP2 were highly expressed in melanoma tissues compared with normal tissue." (PMID 32462000, 2020). "In order to verify whether IQCE, RFX6, GPAA1, BAHCC1, CLEC2B, and AGAP2 were highly expressed in melanoma tissues as predicted, we experimentally confirmed this by qRT-PCR and immunohistochemical staining using melanoma tissues extracted from 10 patients." (PMID 32462000, 2020).
periodontitis (1 paper, 2019). An acute or chronic inflammatory process that affects the tissues that surround and support the teeth. "The most strongly associated signal for this phenotype was in the gene body of the IQCE gene and was hyper-methylated in individuals who presented with tooth mobility, the severe stage of periodontitis." (PMID 30760334, 2019).
tumor (2 papers, 2020 to 2021). "Six characteristic genes (IQCE, RFX6, GPAA1, BAHCC1, CLEC2B, and AGAP2) were selected by random forest feature selection, many of which have been reported to be associated with tumor progression." (PMID 32462000, 2020). "We also found that IFNGR2, IQCE, TRPM4, and SLX4 could be associated with SNU-16 derived tumor growth in female mice by endogenous E2." (PMID 34257587, 2021).
IQCE also shares sentences with these, for which no sentence is quoted: asthma (1 paper); bipolar disorder (1); cancer (1); neuroblastoma (1); polydactyly (1); schizophrenia (1); viral infection (1).